CD4 (CD4 molecule)
Diseases named in the same sentence as CD4 in open-access papers (continued):
Sharing a sentence is not in itself a finding about the gene and the disease.
infection (continued). "The present study illustrates that the effect of Leishmania on HIV-1 replication in a coculture system composed of DCs and CD4+ T cells largely depends on the developmental stage of the parasite and the chronology of infection of DCs by the two pathogens." (PMID 19468304, 2009). "It is now well established that DCs can efficiently transmit HIV-1 to neighbouring CD4+ T cells through both trans- and cis-infection pathways." (PMID 19468304, 2009). "Infection of tissue macrophages assists in the progressive infection of CD4+ T cells due to interactions of the HIV-1 viral protein Nef through stimulation of the CD40 receptor and activation of the NF-κB pathway." (PMID 19674458, 2009). "We then followed the course of viral DNA synthesis and nuclear migration in resting CD4 T cells after infection." (PMID 19851458, 2009). "This phenomenon has been observed at all stages of the infection and is postulated to disrupt the IL-2 producing capacity of CD4+ T cells directed against HIV-1." (PMID 19352428, 2009). "Less is known about HIV-specific CD4+ T cells as these are specifically targeted by the virus as the infection progresses." (PMID 19165342, 2009). "The erythrocyte-bound HIV-1 was then approx 100-fold more infectious, via trans infection, for infection of CD4(+) target cells, and the cell-bound HIV-1 reconstituted essentially all of the infectivity of the original unadsorbed free virus." (PMID 20011536, 2009). "Since the total concentration of CD4+ T cells changes over time, an and am vary over the course of infection." (PMID 19680436, 2009). "Specifically, rate of infection with Cryptosporidium, I. belli, and S. stercoralis were higher, particularly in those with CD4 count less than 200 cells/μL." (PMID 19765310, 2009). "RTS,S-induced CS-specific CD4+ T cell frequency, as enumerated by both ex vivo ELISPOT and intracellular cytokine staining, is associated with protection against infection." (PMID 20042088, 2009). "On the other hand, macrophages get infected early during infection and survive active viral replication, serving as a continuous source of viral progeny especially during the late phases of infection, when CD4+ T cells are being lost." (PMID 20119528, 2009). "Its within-population variability then instead largely relates to pre-infection CD4 levels, which vary by up to a factor ten among uninfected adults without influencing prognosis after infection." (PMID 19536329, 2009). "From previous work we expect that target cell number (the number of uninfected CD4+ T cells available for infection) is important to viral growth and the rate of reversion." (PMID 19360124, 2009). "In BALB/cJ mice P. gingivalis-infection led to a significant increase in the mean percentage of total viable CD4+ T cells compared with sham-infected BALB/cJ mice (P < .05)." (PMID 19859584, 2009). "During stable infection, overall within-subject variation is proportionally larger for RNA than for CD4." (PMID 19536329, 2009). "Median within-population interquartile ranges were 74,000 copies/mL for RNA with no significant change during the course of infection; and 330 cells/μL for CD4, with a slight proportional increase over infection." (PMID 19536329, 2009). "We observed an initial loss of memory CD4+ T cells at peak viremia, as indicated by a higher ratio of naïve to memory CD4+ T cells than before infection in all but one SIV-infected AGM." (PMID 20011508, 2009). "This study also showed that surfactant protein A inhibited the direct infection of CD4+ T cells, suggesting a selection pressure for DC-mediated trans infection at mucosal surfaces." (PMID 19486514, 2009). "An intrathymic or intranodal injection of HIV-1 into the SCID-hu Thy/Liv mouse results in an infection that mimics human viral tropism; that is, preferential infection of CD4+ T cells." (PMID 19674458, 2009).
infection (continued). "Mice were intraperitoneally (i.p.)infected with T. cruzi trypomastigotes, and at 6 days of infection CD4+ T cells were isolated from the spleen and stimulated with anti-CD3 antibody (Ab)." (PMID 19609356, 2009). "Another T-cell cytokine, IL-2, plays a key role during infection by inducing proliferation/activation of CD4+ and CD8+ T cells, potentiates the cytotoxicity of CD8+ T lymphocytes and Natural Killer (NK) cells, and stimulates B lymphocyte function." (PMID 19440245, 2009). "HIV's infection of a CD4+ T cell begins when HIV's outer envelope protein gp120 binds to a CD4 receptor and subsequently binds to one of two chemokine coreceptors, CCR5 or CXCR4." (PMID 19680436, 2009). "The earliest date of confirmed infection ranged between 1984–2005; the median number of CD4 counts used in the calculation of the slope was 9, the median baseline CD4 count was 596 cells/μL, and median age was 28.9 years at entry." (PMID 19478880, 2009). "It has been reported that many decades after infection, relatively high frequencies of gI-specific interferon gamma were detected ex-vivo and are dominated by CD4+ T cells." (PMID 23675158, 2009). "Specifically, it was found that the Treg cells and their interaction with the FoxP3 transcription factor (CD4+FoxP3+ cells) allow for the preferential infection by HIV-1 in the Rag2-/-γc-/- animals." (PMID 19674458, 2009). "Analysis of brain-associated CD4+ and CD8+ T cells after infection with Pb ANKA parasites displayed a constant rise in T cells with similar kinetics in both genotypes until day 5 where a higher number of cells was detected in the brains from H3R−/− mice." (PMID 19547708, 2009). "For example, viruses can directly bind CD4 and the appropriate co-receptor on the plasma membrane of immature mDCs leading to a cytosolic delivery of viral material and productive infection." (PMID 19419540, 2009). "Since CXCR4 is found on a large number of memory CD4+ T cells, we allow for X4's infection of memory as well as naïve CD4+ T cells." (PMID 19680436, 2009). "The number of IFN-γ-producing CD4+ T cells was almost equally elevated in wild-type, Myd88−/− and Myd88−/−Trif−/− mice at 6 days as well as at 10 days after infection." (PMID 19609356, 2009). "HIV-1 vaccines should, therefore, provoke both specific CD8+ and CD4+ T cell responses, so as to maximize the chance of preventing or controlling infection." (PMID 19555490, 2009). "The induction of antigen-specific CD4 Th1 and Th2 responses is important for protection against infection by various types of pathogens." (PMID 19555490, 2009). "In contrast to CD4+ T cells, there was a significant increase in the number of blood pDC between 3 and 6 days post infection, in some instances reaching 7 times that of pre-infection levels, indicative of peracute mobilization of pDC." (PMID 19424421, 2009). "After infection, CD4+ T cell counts and frequencies remained stable in the blood and lymph nodes of AGMs but were rapidly depleted in PTs." (PMID 19214219, 2009). "Further analyses of infection of macaques with CCR5-utilizing SIV strains containing CD8 T cell escape mutations and frequent gut biopsies to assess memory CD4 T cell depletion are warranted." (PMID 19360124, 2009). "The effect of the date of confirmed infection was highly significant (−2.0 cells/μL/year/year; 95% CI: −2.7–−1.3; p<0.001) in the regression analysis, confirming the time trend toward steeper CD4 slopes." (PMID 19478880, 2009). "In CD4-depleted mice with progressive infection, on the other hand, apoptosis of CD8+ and CD19+ lymphocytes begins on week 3 when the infection has been established but then fails to decline." (PMID 19558669, 2009). "Only one of every 10 participating individuals was found to be at relatively early stages of the infection (CD4+ T cell count >500 cells/μL)." (PMID 19664284, 2009).
infection (continued). "Over two decades of observations, the rate of CD4 decline in newly diagnosed infections has almost doubled, while the viral setpoint has been increasing at a rate of about one log per 16 years since RNA measurements had become available." (PMID 19478880, 2009). "The level of infection by progeny viruses was analyzed in CD4+ C88166 T cells by determination of the percentage of infected (GFP-positive) cells with FACS analysis." (PMID 18414671, 2008). "HIV-1 has appropriated this feature of the immune system to better establish and maintain infection of its primary target–CD4-positive T cells." (PMID 18725936, 2008). "We found that both the clearance of primary infection and vaccination require the concerted efforts of CD4 T cells, CD8 T cells, B cells, and that T cells required the effector molecule perforin for maximal impact on MNV infection." (PMID 19079577, 2008). "We find that CD4+ T cells are a significant source of IL-10 by day 5 of both PyL and PyNL infections, since IL-10 mRNA is significantly upregulated in splenic CD4+ cells on days 5 and 7 post-infection compared with cells from uninfected mice." (PMID 18401464, 2008). "At 3 days p.i., the number of infiltrating cells was greater after infection with vΔC16, and more CD4+ and CD8+ T cells were activated (CD69+)." (PMID 18796705, 2008). "Several lines of evidence indicate that ATP is affecting primarily HIV-1 trans-infection of CD4+ T-cells (i.e. early transfer)." (PMID 18373845, 2008). "In African lions (Panthera leo) and other exotic felid species, disease etiology introduced by FIV infection are less clear, but recent studies indicate that FIV causes moderate to severe CD4 depletion." (PMID 18251995, 2008). "For about 10 years post-infection his CD4+ T cell counts were stable, but after another 3 years his CD4+ T cell count fell to 261 and HAART was initiated." (PMID 18808677, 2008). "We previously demonstrated that Vpx of HIV-2/SIVSM was essential for early events in macrophage infection yet dispensable for infection of CD4 lymphocytes." (PMID 18451984, 2008). "An initial transfer phase occurs whereby intact viruses captured by iDCs are transported to the DC-T cell synapse and transferred to CD4+ T cells (i.e. early transfer or trans-infection)." (PMID 18373845, 2008). "In our study, T lymphocytes represented the main infected cell population throughout the MGT while macrophages were predominant over CD4+ T cells in the epididymis and accessory glands prior to infection." (PMID 18347738, 2008). "This was associated with reduced anti-parasitic CD4+ T cell activation in the spleen and lowered hepatic IFNγ, TNF and nitric oxide production by 14 days post infection." (PMID 18802456, 2008). "The fMLF peptide (100 μg/) showed a partial inhibitory effect on infection of NP-2/CD4/FPRL1 cells with GUN-7WT, HCM342, CBL23, or the mndGB-1 strain." (PMID 18577234, 2008). "L’infection par le VIH affaiblit le système immunitaire en détruisant les cellules responsables de la réaction immunitaire (cellules CD4 ou T4) et en se multipliant à l’intérieur de celles-ci." (PMID 21532890, 2008). "We next tested this relationship using primary activated CD4+ T cells as producer cells, transferring virus to target cells on both day 2 and day 3 after infection of the producer cells." (PMID 18613957, 2008). "If so, we predict that HIV-1 specific memory CD4+ T cells that survive during infection secrete anti-viral CCR5 ligands." (PMID 18941536, 2008). "The human retrovirus HIV-1 has been proposed to hijack the natural endocytic function of dendritic cells (DCs) to infect interacting CD4 T cells in a process termed trans-infection." (PMID 18584030, 2008). "In a second, slower process, a productive infection of iDCs results in a potent transfer of newly formed viruses to CD4+ T cells (i.e. late transfer or cis-infection)." (PMID 18373845, 2008).
infection (continued). "During the course of infection, the level of plasma virus fluctuated and correlated inversely with the number of human CD4 T cells in the peripheral blood." (PMID 18237418, 2008). "To explore the effect of CD4-specific DARPins on HIV entry we evaluated the inhibitory activity of our panel of CD4-DARPins in vitro using a standardized assay system based on infection of TZM-bl reporter cells with envelope pseudotyped HIV particles." (PMID 18654624, 2008). "In HIV-infected patients on long-term HAART, virus persistence in resting long-lived CD4 T cells is a major barrier to curing the infection." (PMID 18827929, 2008). "TZM-bl cells, which are permissive to HIV-1NL4-3 infection, express the viral receptor CD4 and coreceptors CCR5 and CXCR4." (PMID 18414664, 2008). "To determine if the effect of TCR signaling was unique to HIV-1, we treated mouse CD4+ T cells in the same way during infection with MLV." (PMID 18446227, 2008). "They contrasted considerably with R5 envelopes from immune tissue (lymph node) that conferred inefficient macrophage infection and required high amounts of CD4 for infection." (PMID 18205925, 2008). "Perhaps in concert with protection of harbored virus, we also showed that P. gingivalis-mediated upregulation of CCR5 in TERT-2 cells increases the effectiveness of trans infection to permissive TZM-bl cells (CD4+ CXCR4+ CCR5+)." (PMID 18371227, 2008). "In contrast, SHIVDH12R or SHIVKU1 use CXCR4 for infection, which is preferentially expressed on naïve CD4+ T cells." (PMID 18928523, 2008). "Early in infection the HIV-1 population usually consist of a strain that has the capacity to bind to both CD4 and the co-receptor CCR5 (R5 strain)." (PMID 18312662, 2008). "Further assessment of their application as microbicides is clearly feasible, particularly as we selected several molecules that are specific for human and rhesus macaque CD4, which will allow future study of their efficacy in the macaque infection model." (PMID 18654624, 2008). "Purified mouse and human resting CD4+ T cells were infected at different multiplicities of infection (MOIs) with JRCSF (R5 HIV-1) containing Vpr-β-lactamase." (PMID 18446227, 2008). "In HIV-1 disease, infection of CD4 T cells leads to their eventual decline whereas infection of monocytes/macrophages and dendritic cells leads to continued viral spread and defects in antigenic presentation thus exacerbating the disease process." (PMID 18215326, 2008). "A significant increase in the number of CD4+ T cells was detected in the lungs of WT H17-memory mice 4 days after PR8 infection compared to naïve mice infected 4 days previously with the PR8 virus." (PMID 18389078, 2008). "CD4+ T cells in HIV mono infection group were consistently lower than that in HIV/HCV group (p = 0.04, 0.18, 0.03 and 0.04 for baseline, month 9, month 21 and month 33 visit, respectively)." (PMID 19098990, 2008). "The pattern of T cell activation was similar to that observed for s.c. infection with WSN-gB infection in C57BL/6 mice with strong proliferation observed for CD4+ and CD8+ T cells peaking around days two and three." (PMID 18301768, 2008). "Activated CD4+ T cells migrate to the site of infection and produce cytokines and chemokines, especially IFN-γ, which serves to recruit and activate macrophages promoting granuloma formation and the inflammatory process." (PMID 18560543, 2008). "A large number of syncytia were formed in the infection of NP-2/CD4/FPRL1 cells with the AG206, HCM342, and mSTD104 isolates, suggesting that replication of HIV-1 efficiently occurred in these cells (data not shown)." (PMID 18577234, 2008). "Alternately, we cannot exclude the possibility that the up-regulation of IFN-γ expression is by specific CD4 memory T cells that are rapidly recruited to the site of infection." (PMID 18414648, 2008).
infection (continued). "On day 5 post-infection, IL-10+ CD4+ T cells showed very variable expression of CD25 with approx. 60% being CD25−, indicating that they are not a typical nTreg population." (PMID 18401464, 2008). "CXCR4 was shown to be selectively down-regulated from the cell surface by HIV-2/vcp in the context of CD4-independent infection or from cells infected with CD4-independent HIV-1 isolate that enters directly via CXCR4." (PMID 18190699, 2008). "Productive infection of CD4+ cells with HIV-1 markedly reduces cell-surface expression of CD4, which follows a classic mechanism for retroviral interference." (PMID 18190699, 2008). "Full suppression of viremia and a CD4+ T-cell count rise were observed until eight months after infection, when treatment was suspended following the request of the patient." (PMID 18648518, 2008). "At 12 months post infection, these individuals also had significantly lower viral loads and higher CD4+ counts (median log VL 4.26 vs. 4.92, p = 0.0275 and median CD4+ count 499.0 vs. 322.5, p = 0.0172)." (PMID 18369479, 2008). "After infection with L. major, the difference in percentage of CD4+CD25+ cells induced by BPA was more notable between BPA-exposed and nonexposed groups in BALB/c mice, but not in C57BL/6 mice." (PMID 18414636, 2008). "When compared to cells that do not express DC-SIGN, preservation of viral infectivity results in an increase in trans infection to CD4+ permissive cells." (PMID 18371227, 2008). "The RFP signal is predicted to remain associated with the virus after binding to the DC prior to trans-infection and lost after CD4-dependent entry into the target cells." (PMID 18725936, 2008). "These cells become sufficiently numerous at around day 5 (for CD8+ T cells) or day 6 (for CD4+ T cells) to allow their detection by flow cytometry, and their numbers peak at ∼7–10 days after infection." (PMID 18404208, 2008). "Several subsequent studies suggested that synthesis of CCR5 ligands by ex vivo CD4+ T cells correlates with resistance of these cells to infection and indicated an inverse relationship between CCR5 ligand synthesis and lower co-receptor levels." (PMID 18941536, 2008). "Pretreatment of the TZM-bl cells with anti-CD4 mAb B4 reduced subsequent trans infection to background levels indicating that CD4 remains essential for infection in this model." (PMID 18414664, 2008). "At day 4 post-infection, however, the cell numbers had increased explosively; both CD4+ and CD8+ T cells had increased in abundance by >100-fold, indicative of the cells' having divided at least 6–7 times in the ∼24 hour period between sample harvests." (PMID 18404208, 2008). "It is well established that paracrine secretion of anti-viral CCR5 ligands by CD8+ and CD4+ T cells can block the infection of activated CD4+ T cells by R5 and dual-tropic isolates of HIV-1." (PMID 18941536, 2008). "DCs efficiently bind and degrade HIV, however a portion of the virus remains intact and can be transmitted into CD4 T cells, a process called trans-infection." (PMID 18725936, 2008). "The second phase (i.e. late transfer or cis-infection) is dependent on productive infection of DCs and eventual transfer of progeny virus to CD4+ T cells." (PMID 18373845, 2008). "The fMLF peptide also partially inhibited infection of NP-2/CD4/CCR5 cells with several HIV-2 or SIV strains." (PMID 18577234, 2008). "Many of our observations are concordant with analysis of LTNP infection status in 2000, which revealed normal CD4+ T-cell levels (>550 cells per μl) suggesting the absence of significant HIV-mediated T-cell targeting and depletion." (PMID 18638397, 2008). "For example, at 9 wk post-infection, the percentage of CD4+ T cells that were IL-13 positive was 17.1% and 11.8% in WT and CAT2−/− mice, respectively, while only 0.19% and 0.2% were IL-17 positive." (PMID 18369473, 2008). "In both cases, LFA-1 increases viral infectivity and directs infection towards CD45RO+ memory CD4 T cells." (PMID 18377648, 2008).